TAF11L11 (TATA-box binding protein associated factor 11 like 11)
Gene: Protein-coding gene on chromosome 5 (17,604,177 to 17,605,910, forward strand). Ensembl gene ENSG00000283740.
Gene Ontology:
Molecular function: RNA polymerase II general transcription initiation factor activity; protein heterodimerization activity
Biological process: RNA polymerase II preinitiation complex assembly; transcription initiation at RNA polymerase II promoter
Cellular component: transcription factor TFIID complex; nucleus
Homologues: Orthologues: zebrafish taf11 (47% identical), tropical clawed frog taf11 (46% identical), Drosophila melanogaster Taf11 (43% identical), Caenorhabditis elegans taf-11.1 (36% identical), Caenorhabditis elegans taf-11.2 (30% identical). Paralogues in human: TAF11L12 (93% identical), TAF11L2 (89% identical), LINC02218 (89% identical), TAF11L13 (86% identical), TAF11L10 (85% identical), TAF11L5 (85% identical), TAF11L6 (85% identical), TAF11L7 (85% identical), TAF11L8 (85% identical), TAF11L3 (84% identical), TAF11L4 (84% identical), TAF11L9 (84% identical), and 2 more.